HAPLN1 (hyaluronan and proteoglycan link protein 1)
Diseases named in the same sentence as HAPLN1 in open-access papers (continued):
Sharing a sentence is not in itself a finding about the gene and the disease.
osteoarthritis (5 papers, 2017 to 2025). A noninflammatory degenerative joint disease occurring chiefly in older persons, characterized by degeneration of the articular cartilage, hypertrophy of bone at the margins and changes in the synovial membrane. "SNPs in HAPLN1 have also been associated with spinal osteophyte formation in osteoarthritis." (PMID 27864696, 2017). "We found that one of the most significantly up-regulated genes in RA-FLSs, contrary to osteoarthritis (OA)-FLSs, is HAPLN1, whose protein level increases in the plasma and synovium of RA patients." (PMID 35720292, 2022). "Nevertheless, genomics research has enabled the clarification of the relation of HAPLN1 with various rheumatic disorders [including spinal degeneration, osteoarthritis (OA), ankylosing spondylitis (AS), and RA]." (PMID 35720292, 2022). "Recent studies have shown that in bone diseases in humans, such as osteoarthritis and allograft transplantation, there is always a low HAPLN1 expression." (PMID 32493207, 2020).
breast cancer (4 papers, 2021 to 2026). A primary or metastatic malignant neoplasm involving the breast. "Stratification of patients by gene expression revealed an overall survival advantage for breast cancer patients with lower Vtn expression or higher Hapln1 expression." (PMID 38773982, 2024). "As our studies revealed two candidate ligand-receptor pairs, Vtn-C1qbp and Hapln1-Vcan, we further analyzed the correlation between the levels of Vtn and Hapln1 and the prognosis of basal-like breast cancer." (PMID 38773982, 2024). "Carcinoma EVs shared 60 over-represented proteins, including ECM proteins involved in cell adhesion, motility, wound healing and maintenance of cell shape (FN1, BGN, HAPLN1), which have all been previously identified in human breast cancer and canine mammary cancer studies." (PMID 39462388, 2024). "Serum samples from 154 dogs with mammary tumors (31 benign, 123 malignant) and 39 healthy controls were analyzed using a custom multiplex immunoassay detecting autoantibodies against AGR2, HAPLN1, IGFBP5, and TYMS, normalized to anti-BSA levels." (PMID 41562247, 2026).
hepatocellular carcinoma (4 papers, 2016 to 2023). A malignant tumor that arises from hepatocytes. "For example, high HAPLN1 expression in lung tumors of mesothelioma patients, liver tumors of hepatocellular carcinoma patients, and triple-negative breast cancer patients with a TME that promoted immune evasion positively correlated with shorter overall survival (OS)." (PMID 36625202, 2023).
rheumatoid arthritis (4 papers, 2022 to 2025). A chronic, systemic autoimmune disorder characterized by inflammation in the synovial membranes and articular surfaces. "The expression of HAPLN1 has been observed to be increased in several types of musculoskeletal diseases, including rheumatoid arthritis." (PMID 38791371, 2024). "An increase in HAPLN1 expression is observed in a few types of musculoskeletal diseases including rheumatoid arthritis (RA); however, its functions are obscure." (PMID 35720292, 2022). "Interestingly, HAPLN1 expression is elevated in certain musculoskeletal diseases, such as rheumatoid arthritis (RA)." (PMID 41083899, 2025).
colorectal cancer (3 papers, 2016 to 2024). A primary or metastatic malignant neoplasm that affects the colon or rectum. "In colorectal cancer cells, reduced HAPLN1 levels were associated with the activation of the TGF-β/SMAD pathway and increased collagen production." (PMID 38562556, 2024). "In contrast, overexpression of HAPLN1 in colorectal cancer cells led to a decrease in the migration of these cells and tumor size." (PMID 38562556, 2024).
mesothelioma (3 papers, 2021 to 2023). A usually malignant and aggressive neoplasm of the mesothelium which is often associated with exposure to asbestos. "High expression of HAPLN1 could upregulate the tumorigenicity of mesothelioma." (PMID 35395711, 2022). "Previous studies have reported that overexpression of HAPLN1, one of the ECM proteins, increases tumorigenic properties of mesothelioma." (PMID 33849532, 2021).
cardiomyopathy (2 papers, 2017 to 2022). A disease of the heart muscle or myocardium proper. "Analysis of pathways that were dysregulated across cardiomyopathy phenotypes identified shared genes that were associated with extracellular matrix remodeling and thus likely fibrosis (THY1, CILP, OGN, THBS4, ASPN, HAPLN1,and SMOC2), as well as calcium (ADIPOQ, ASPN, THBS4, STAT4, and SMOC2)." (PMID 28098235, 2017).
dwarfism (2 papers, 2014 to 2016). "Remarkably, the mouse knockout for CRTL1 (aka HAPLN1) causes dwarfism, craniofacial abnormalities, and perinatal lethality in the mouse." (PMID 24533114, 2014). "The mouse knockout for CRTL1 (aka HAPLN1) results in perinatal lethality, dwarfism, delayed ossification, short limbs, defects in cartilage and bone development and craniofacial abnormalities showing that CRTL1 is both essential and critical for proper skeletal development." (PMID 26828861, 2016).
glioma (2 papers, 2012 to 2025). A benign or malignant brain and spinal cord tumor that arises from glial cells (astrocytes, oligodendrocytes, ependymal cells). "All three DEGs encoding proteoglycans (HAPLN2, ACAN and HAPLN1) showed higher transcript enrichment in the grade 2 gliomas in comparison to the matched normal samples." (PMID 41366031, 2025). "TargetScan identified that HAPLN1 is targeted by hsa-miR-23, but HAPLN1 can also trigger upregulation of miR-21, which was previously shown to serve an essential role in the malignant progression of human gliomas." (PMID 23056502, 2012).
lung fibrosis (2 papers, 2021 to 2023). "The upregulated HAPLN1 encodes a hyaluronan and proteoglycan link protein involved in collagen organization and immune cell infiltration in dermal fibroblasts and the modulation of myofibroblasts in pulmonary fibrosis." (PMID 36835058, 2023). "HAPLN1 induced by TGFβ in lung fibroblasts is thought to be involved in lung fibrosis." (PMID 34777248, 2021).
pancreatic cancer (2 papers, 2023 to 2024). "Here the authors show that hyaluronan and proteoglycan link protein-1 (HAPLN1) promotes tumour cell plasticity and pro-tumoral immune microenvironment to facilitate peritoneal dissemination in pancreatic cancers." (PMID 37095087, 2023). "In summary, these data demonstrate that HAPLN1 expression remodels the ECM and promotes EMT and stemness of pancreatic cancer cells." (PMID 37095087, 2023).
pleural mesothelioma (2 papers, 2016 to 2021). A neoplasm that arises from the mesothelial cells of the pleura. "Also, HAPLN1 has been associated with bad outcome in pleural mesothelioma." (PMID 27191501, 2016). "HAPLN1 gene expression is increased in lung tissues from patients with pleural mesothelioma compared with healthy controls, while some other studies showed HAPLN1 levels decreased during aging, and this is potentially involved in cancer invasion." (PMID 34966673, 2021).
achondroplasia (1 paper, 2022). Achondroplasia is the most common form of chondrodysplasia, characterized by rhizomelia, exaggerated lumbar lordosis, brachydactyly, and macrocephaly with frontal bossing and midface hypoplasia. "Perinatal mice with inactivated HAPLN1 developed lethal achondroplasia, with their extremities and vertebral cartilage lacking proteoglycan deposition and having a reduced number of hypertrophic chondrocytes." (PMID 35720292, 2022).
ankylosing spondylitis (1 paper, 2022). An autoimmune chronic inflammatory disorder characterized by inflammation in the vertebral joints of the spine and sacroiliac joints. "The HAPLN1 gene is present adjacent to the ankylosing spondylitis-associated single nucleotide polymorphism (SNP) (rs4552569)." (PMID 35720292, 2022).
cardiac hypertrophy (1 paper, 2024). "Altogether, in the present study, we found that HAPLN1 knockdown suppressed cardiac hypertrophy and oxidative stress in HF." (PMID 38580957, 2024). "In conclusion, silencing HAPLN1 significantly promoted Ang II-induced AC16 cellular viability, reduced apoptosis, inhibited cardiac hypertrophy and oxidative stress." (PMID 38580957, 2024). "In the present study, we found that knockdown of HAPLN1, a key gene in the ECM, significantly promoted HF cell viability and reduced apoptosis, cardiac hypertrophy and oxidative stress response, which has not been reported before." (PMID 38580957, 2024).
Cirrhosis (1 paper, 2016). A chronic disorder of the liver in which liver tissue becomes scarred and is partially replaced by regenerative nodules and fibrotic tissue resulting in loss of liver function. "HAPLN1 was detected at much higher levels in HCCs than in non-tumor livers in our cohort, as well as in 80 HCCs with respect to 307 non-tumor hepatitis/cirrhosis livers in a public DASL microarray dataset (GSE10143)." (PMID 27191501, 2016).
colorectal tumors (1 paper, 2023). "Computational analyses from triple-negative breast tumors and colorectal tumors also identified high HAPLN1 expression with the regulation of inflammatory and immune cytokines as part of its pathobiology." (PMID 36625202, 2023).
COVID-19 (1 paper, 2022). A disease caused by infection with severe acute respiratory syndrome coronavirus 2. "More specifically, through clustering analysis, the down-regulated DEPs of the si-HAPLN1 group were enriched in S. aureus infection, SLE, TNF signaling pathway, COVID-19, and ribosome." (PMID 35720292, 2022).
dementia (1 paper, 2023). Loss of intellectual abilities interfering with an individual's social and occupational functions. "In group comparisons between non-demented controls and dementia samples we found significant differences only for HAPLN1 transcript levels in the HC." (PMID 36982604, 2023).
intervertebral disc degeneration (1 paper, 2024). "HAPLN1 has been implicated in the degradation of the extracellular matrix and the process of intervertebral disc degeneration in both humans and animals." (PMID 38803805, 2024).
keloid (1 paper, 2026). An irregularly shaped, elevated mark on the skin caused by deposits of excessive amounts of collagen during wound healing. "Subsequent network topology analysis through CytoHubba identified six hub genes (IL6, POSTN, VCAN, COL11A1, HAPLN1, TNC) via three methods of calculation respectively (Closeness, Degree and EPC), representing key regulatory nodes in the keloid." (PMID 41544047, 2026).
metastatic melanoma (1 paper, 2022). A melanoma that has spread from its primary site to another anatomic site. "HAPLN1 regulates cell growth in the developing cartilage and heart valves, and is expressed in mesoderm‐committed embryonic stem cells, cancer cells undergoing epithelial‐mesenchymal transition (EMT), and metastatic melanomas." (PMID 35716037, 2022).
Seizure (1 paper, 2018). A seizure is an intermittent abnormality of nervous system physiology characterized by a transient occurrence of signs and/or symptoms due to abnormal excessive or synchronous neuronal activity in the brain. "Indeed a number of seizure models show downregulation of the PNN components aggrecan, hyaluronan and proteoglycan link protein 1 (HAPLN1) and hyaluronan synthease-343." (PMID 30413686, 2018).
ulcerative colitis (1 paper, 2024). An inflammatory bowel disease involving the mucosal surface of the large intestine and rectum. "In an RNA sequencing profile comparing colonic mesenchyme between healthy and ulcerative colitis mice, glial cells were typically clustered by the expression of their markers S100B and GFAP, and possible additional markers include Hapln1 and POSTN." (PMID 37551711, 2024).
tumor (30 papers, 2014 to 2026). "Upregulated HAPLN promotes peritoneal dissemination and elevated expression of HAPLN1 in CAFs is associated with an aggressive phenotype, poor prognosis, and tumour progression in GC." (PMID 38791985, 2024). "Recently, CAF-derived HAPLN1 was found to fuel tumor cell invasion in gastric cancer and was associated with worse overall survival in pleural mesothelioma and drug resistance in multiple myeloma." (PMID 37095087, 2023). "We proposed that these changes of ECM are associated with increase of tumour invasiveness induced by HAPLN1." (PMID 34724589, 2022). "We have also shown that epithelial, stromal, and endothelial cells and myofibroblasts express HAPLN1 gene in the colon by RNA-sequencing, but only epithelial cells are associated with tumor formation in CRC." (PMID 34966673, 2021). "Since T cells use collagen fibrils to infiltrate tumors, downregulating HAPLN-1 expression in melanoma models results in decreased CD3+ T cell infiltration associated with increased tumor cell extravasation." (PMID 31134198, 2019). "Among the genes switched on within this network, HAPLN1 is associated with bad outcome and with the expression of markers of stemness and of tumor aggressiveness." (PMID 27191501, 2016). "Additionally, in hepatocellular carcinoma HAPLN1 is expressed by tumor cells and associated with EMT22." (PMID 37095087, 2023). "The loss of function of HAPLN1 during ageing has a significant effect on tumour cell motility." (PMID 35884596, 2022). "Importantly, HAPLN1, mainly produced by cancer-associated fibroblasts (CAFs), was also detected in the tumor tissues in the zPDX models." (PMID 34164399, 2021). "GSEA analysis of RNA-Seq data also showed that HAPLN1 is not only linked to pathways related to drug resistance but it may have a wider role in orchestrating the intra-tumoral inflammatory milieu and balancing anti-tumor immunity." (PMID 36480501, 2022). "Based on a quantitative comparison between tumor and NAT ECM, we observed a substantial loss of PROs (i.e., DCN, OGN, LUM, and HAPLN1)." (PMID 40032993, 2025). "COL12A1 and THBS2 showed enriched expression in tumor tissue section and hyaluronan and proteoglycan link protein 1 (HAPLN1) showed enriched expression in NAT tissue section." (PMID 40032993, 2025). "An upregulation of HAPLN1 in cancer-associated fibroblasts (CAF) has been reported in GC, which is associated with an aggressive phenotype, poor prognosis, and tumour progression." (PMID 38791985, 2024). "In vivo, SERPINH1 and HAPLN1 were validated to tumor-enriched and NAT-enriched proteins, each with IHC." (PMID 39305996, 2024). "To evaluate the role of HAPLN1 expression in invasion, we embedded tumor cell spheroids into Matrigel and evaluated their invasive potential." (PMID 37095087, 2023). "To explore the effects of HAPLN1 on EMT, stemness and invasion in vivo, we used a model for peritoneal carcinomatosis, injecting RFP and luciferase-expressing KPC and KPC-HAPLN1 cells intraperitoneally (i.p.), to mimic an advanced tumor stage." (PMID 37095087, 2023). "HAPLN1 is also involved in the proliferation and activation of fibroblasts in lung tissue, synovial tissue, and tumor tissue." (PMID 37784143, 2023). "Here, we show that the presence of hyaluronan and proteoglycan link protein-1 (HAPLN1) in the extracellular matrix enhances tumor cell plasticity and PDAC metastasis." (PMID 37095087, 2023). "Relative to the total, dKO tumours were enriched in NC Zeb2 cells to the detriment of NC arrested and Hapln1 cells." (PMID 37605008, 2023). "Our work identifies the extracellular protein HAPLN1 as a driver of tumor cell plasticity, promoting EMT, stemness, invasion and immunosuppression in a paracrine manner." (PMID 37095087, 2023). "Nevertheless, more investigation is needed to gain better mechanistic and overall understanding of HAPLN1 action within the tumor microenvironment." (PMID 37095087, 2023).
tumor (continued). "In a mouse model for peritoneal carcinomatosis, HAPLN1-induced immunomodulation favors a more permissive microenvironment, which accelerates the peritoneal spread of tumor cells." (PMID 37095087, 2023). "While immune and stromal cells expressed HAPLN1 mRNA in both normal and tumoral tissue, only the epithelial cells significantly increased HAPLN1 expression upon their transformation to tumor cells." (PMID 37095087, 2023). "Ratios of the three AAbs, in particular IGFBP5-AAb and HAPLN1-AAb, noticeably declined at 3 and 12 months after tumor resection (respectively), albeit the reduction in the ratio of TYMS-AAb was not statistically significant." (PMID 36139323, 2022). "Nude mouse studies indicated that the tumour volume in MKN45/CAFs-sh HAPLN1 group was smaller than that in MKN45/CAFs group (P < 0.001), indicating that HAPLN1 knockdown in CAFs can inhibit MKN45 tumourigenesis in vivo." (PMID 34724589, 2022). "MKN45 cells and CAFs with different HAPLN1 levels were inoculated into Balb/c nu/nu mice subcutaneously and established xenograft tumours." (PMID 34724589, 2022). "The upregulated genes, including WNT11, HAPLN1, FGF10, BBOX1, CXADR, NDP, and EREG are associated with tumor proliferation, migration, and cancer stemness." (PMID 35954313, 2022). "HAPLN1 was prominently produced by CAFs, and its levels were correlated positively with tumor T staging (P < 0.0001), lymph node metastasis (P = 0.0006) and TNM stage (P = 0.0063)." (PMID 34724589, 2022). "Collectively, the studies of human tumour tissues further confirm that CAFs-derived HAPLN1 is a key factor that drives tumour invasion through ECM remodeling." (PMID 34724589, 2022). "IHC and immunofluorescence assays with human tumour samples showed that TGF-β1 expression in cancer cells was correlated with HAPLN1 expression in CAFs." (PMID 34724589, 2022). "We will pursuit our future research to investigate HAPLN1 regulation in stomach to elucidate its detailed roles in gastric tumourgenesis and tumour progress." (PMID 34724589, 2022). "To further dissect the origin of HAPLN1 in the tumour microenvironment, we demonstrated that HAPLN1 was expressed prominently in CAFs in cancer tissues and in NFs in normal tissue as well." (PMID 34724589, 2022). "We found that the HAPLN1 expression in Hs738 cells was significantly increased in a time-dependent manner after treatment with tumour CM." (PMID 34724589, 2022). "HAPLN1 mRNA levels were also decreased in tumor compared with normal tissues adjacent to tumor tissues in the same CRC patients." (PMID 34966673, 2021). "To further assess the level of HAPLN1 in CRC patients, we measured HAPLN1 mRNA in tumor tissues and their normal tissues adjacent to the tumor in CRC patients using another microarray dataset (GSE110224)." (PMID 34966673, 2021). "We also found that decreased HAPLN1 negatively correlated with collagen expression and contributes to tumor development in CRC." (PMID 34966673, 2021). "The HAPLN1 protein was decreased in tumor (stage I–IV cancer) compared with normal tissues adjacent to tumor tissues (mean = 35.56 vs. 22.73)." (PMID 34966673, 2021). "In this study, HAPLN1 mRNA and protein levels were measured in tumor, normal tissue adjacent to tumors, and healthy control tissue in existing microarray datasets and protein tissue arrays." (PMID 34966673, 2021). "We also show that decreases in HAPLN1 proteins are associated with increased COL1A1 protein levels in CRC epithelial cells after TGF-β challenge and control tumor growth." (PMID 34966673, 2021). "Other genes included those that encode members of the proteoglycan family (HAPLN1, SPOCK3) and influence ECM structure in the tumor microenvironment and urotensin 2 (UTS2) which has known roles in regulation of angiogenesis." (PMID 34162930, 2021). "A potential mechanism is that HAPLN1 regulates tumor cell proliferation via the TGF-β (Smad2/3, p-Smad2/3, and Smad4) signaling pathway." (PMID 34966673, 2021).